LINC02073 (long independently transcribed non-coding RNA 2073)
Synonyms: LINC02072
Gene: Long non-coding RNA gene on chromosome 17 (51,336,644 to 51,521,402, forward strand). Ensembl gene ENSG00000267452.
Diseases named in the same sentence as LINC02073 in open-access papers:
LINC02073 is named in the same sentence as 1 disease in open-access papers, as found by Europe PMC text mining. Sharing a sentence is not in itself a finding about the gene and the disease. The quoted sentences say what the papers report.
Stroke (1 paper, 2023). Sudden impairment of blood flow to a part of the brain due to occlusion or rupture of an artery to the brain. "Non-coding genes LINC00870, LINC01206, LINC01287, and LINC02073 are mainly more highly expressed in stroke patients, so they are upregulated." (PMID 37508918, 2023).